ENSG00000284461 (novel transcript)
Gene: Protein-coding gene on chromosome 7 (66,628,958 to 66,811,189, forward strand). Ensembl gene ENSG00000284461.
Genetic constraint (gnomAD): Missense variants: 223 observed, 231.73 expected, observed/expected ratio (o/e) 0.96, 90% interval 0.86 to 1.08. Synonymous variants: 97 observed, 91.65 expected, observed/expected ratio (o/e) 1.06, 90% interval 0.9 to 1.25.